PARP1 (poly(ADP-ribose) polymerase 1)
Diseases named in the same sentence as PARP1 in open-access papers (continued):
Sharing a sentence is not in itself a finding about the gene and the disease.
breast tumors (31 papers, 2010 to 2025). "In 2006, De Soto evaluated the sensitivity of multiple cell lines (non-cancerous mouse embryonic stem cells and hamster cells; human and mouse breast tumor cells) with BRCA1 or BRCA2 deficiency to three PARP1 inhibitors (NU1025, 3-aminobenzamide, and AG14361)." (PMID 29069872, 2017). "As this is consistent with previous results, PARP1 inhibition might be a possible therapeutic approach to treat patients with breast tumors associated with germline FANCM pathogenic variants." (PMID 31700994, 2019). "In addition, consistent with a BRCA1-deficiency phenotype, miR-182-overexpressing breast tumor cells are hypersensitive to the inhibitors of poly (ADP-ribose) polymerase I (PARP1)." (PMID 30135399, 2018). "As observed in ovarian and breast tumours, targeting poly (ADP-ribose) polymerase 1 (PARP1) in tumours with BRCA1 and breast cancer gene 2 (BRCA2) inactivation selectively causes cancer cell death, showing promise in clinical settings." (PMID 39271762, 2024). "PARP1 gains and amplifications were present in primary ovarian tumors (43%), recurrent ovarian tumors (32%), primary breast tumors (62%), and recurrent breast tumors (78%)." (PMID 36344544, 2022). "Both KLF4 and PARP1 protein levels were significantly higher in breast tumor tissues than in adjacent normal tissues." (PMID 33231937, 2020). "PARP1 mutant SUM149 cells had the most profound PARPi-resistant phenotype seen amongst 38 molecularly diverse breast tumour cell lines." (PMID 29748565, 2018). "Whereas to human and mouse breast tumor cells tested, the PARP1 inhibitors were either ineffective or eliminate these cells irrespective of BRCA1 status." (PMID 29069872, 2017). "Clinical data of Domagala’s group showed that nuclear PARP1 expression was upregulated in most breast tumors, while the overexpression of nuclear–cytoplasmic PARP1 was present only in a small percentage of breast tumors." (PMID 28991194, 2017). "miR-361-5p and miR-151-5p were found to be overexpressed in PARP1-upregulating BRCA-germline mutated and sporadic breast tumors." (PMID 27385001, 2016). "In studies of breast tumors, PARP-1 expression was correlated with higher grade and estrogen receptor (ER) negative status, suggesting that PARP-1 was over-expressed in more aggressive tumor subtypes." (PMID 24202328, 2013). "Previously, we have shown that low RECQL breast tumors were significantly associated with low PARP1, BRCA1 negative, low RAD51, low ATM, low nuclear pChk1, low nuclear Chk2, low XRCC1, low FEN1, low SMUG1, and low DNA-PKcs expression." (PMID 38134458, 2023). "Furthermore, reduced expression of Let-7a is reported in HER2+ breast tumors compared to HER2-, and is inversely associated with the expression of DNA repair protein, PARP1." (PMID 34572725, 2021). "Ovarian and breast tumors with BRCA1 and BRCA2 mutations are sensitive to the PARP1 inhibitors." (PMID 31856867, 2019). "Another study shows that miR-151-5p is upregulated in PARP1-overexpressing BRCA-mutated and sporadic breast tumors, which eventually could be considered as BRCAness tumors." (PMID 30934991, 2019). "Talazoparib and Olaparib are two drugs used to target PARP1 and PARP2 genes that could be mutated in advanced breast tumors." (PMID 30538267, 2018). "Because PARP-1 is involved in angiogenesis, we next investigate the impact of the PARP inhibitor (PARPi) on the VM formation of three breast tumor cell lines and an endothelial cell line." (PMID 36555812, 2022). "We then observed (over two-fold) increases for PARP1 expression in primary and recurrent breast tumors, as well as ovarian recurrences, independent of PARP1 copy number." (PMID 36344544, 2022).
breast tumors (continued). "Unlike ZC3H12A, which induces apoptosis in breast tumor cells, ZC3H12D did not substantially increase the levels of cleaved PARP1 and Caspase3, two apoptosis indicators." (PMID 41263459, 2025).
acute myeloid leukemia (30 papers, 2013 to 2025). Acute myeloid leukemia (AML) is a group of neoplasms arising from precursor cells committed to the myeloid cell-line differentiation. "report that PARP-1-mediated programmed cell death, parthanatos, is associated with the successful frontline treatment of certain acute myeloid leukemias (AMLs)." (PMID 37683650, 2023). "Fatigue, anemia, nausea and neutropenia together with a risk of myelodysplastic syndrome/acute myeloid leukemia accompany the use of synthetic PARP1/2 inhibitors." (PMID 35873588, 2022). "For example, acute myeloid leukemia (AML) stem cells evaded killing by NK cells through increased expression of the DNA repair enzyme poly-ADP-ribose-polymerase 1 (PARP1), which caused a repression of NKG2D ligands." (PMID 35565467, 2022). "PARP1 overexpression has been correlated with poor survival outcomes in acute myeloid leukemia (AML)." (PMID 40904702, 2025). "In several solid tumours, including breast, ovarian, lung, liver, brain, oesophagus, pancreas, skin, stomach, and acute myeloid leukaemia, high expression of PARP-1 has been related to poorer survival rates." (PMID 36902215, 2023). "In acute myeloid leukemia, inhibition of PARP1 induced neoplastic cell apoptosis and arrested cell cycle in G2/M phase." (PMID 32380691, 2020). "On the other hand, in acute myeloid leukemia PARP1 is involved in repression of NK cell activity by downregulation of NK cell-activating receptor ligands." (PMID 32380691, 2020). "While the PARP-1 invalidation or olaparib treatment inhibits the expression and the phosphorylation of NF-kB in small-cell lung cancer, olaparib treatment activates NF-kB in acute myeloid leukemia blasts." (PMID 36555812, 2022). "The differentially expressed transcripts and proteins, predicted transcriptional factors, and key molecules such as HIC1, CEBPB, LYN, and PARP1 may be considered as potential targets for differentiation therapy of acute myeloid leukemia." (PMID 34207065, 2021). "In addition, PARP-1 is involved in the downregulation of NK cell-activating receptor ligands for immune evasion in acute myeloid leukemia." (PMID 32046278, 2020). "In our studies we showed that in the bone marrow cells of patients with acute myeloid leukemia, PARP1 and PARP2 genes are overexpressed and TRPM2 gene is down-regulated, which may suggest disturbed signaling between these genes." (PMID 32423430, 2020). "Interestingly, the bone marrow cells of patients with acute myelogenous leukemia show over expression of PARP1 and PARP2 genes and decreased TRPM2 gene expression." (PMID 32423430, 2020). "In acute myelogenous leukemia cells, PARP1, PARP2, and TRPM2 gene mRNA levels deregulate." (PMID 32423430, 2020). "Moreover, the orphan snoRNA SNORA73 can combine with PARP-1 and the H/ACA box RNP core proteins DKC1/NHP2 to form a snoRNP at DNA damage genomic loci, which blocks PARP-1 autoPARylation and DNA damage repair and leads to genome instability and cell differentiation in acute myeloid leukemia." (PMID 38406265, 2024). "PARP1 was also found in acute myeloid leukemia and is suggested to be an independent prognostic factor in AML." (PMID 32423430, 2020). "The highest PARP1 gene expression was found in acute myeloid leukemia cells (AML), while the lowest PARP1 gene expression was detected in the group of hematopoietic stem cells collected from the peripheral blood after mobilization (PBSC)." (PMID 32423430, 2020). "The results found that the bone marrow cells of the patients with acute myeloid leukemia (AML) show overexpression of PARP1 and PARP2 genes and decreased TRPM2 gene expression." (PMID 32423430, 2020). "Malignant hematopoietic cells of myelodysplastic syndromes (MDS)/chronic myelomonocytic leukemias (CMML) and acute myeloid leukemias (AML) may be vulnerable to inhibition of poly(ADP ribose) polymerase 1/2 (PARP1/2) and apurinic/apyrimidinic endonuclease 1 (APE1)." (PMID 31623402, 2019).
acute myeloid leukemia (continued). "In acute myeloid leukemia (AML), patients with high PARP1 expression had significantly shorter overall survival and free survival times compared with the low-expression group." (PMID 39200230, 2024). "In acute myeloid leukemia (AML) with internal tandem duplications of fms-like tyrosine kinase 3 (FLT3-ITD), PARP1 is indispensable for STAT5 activity through interacting and PARylating STAT5 to prevent its proteasomal degradation." (PMID 36909172, 2023). "Although poorly characterized, the interplay between PARP1 and NPM1 was shown to be functional for treatment of acute myeloid leukemia." (PMID 33804735, 2021). "Our research suggests that there is a different regulation of PARP1, PARP2, PARP3, and TRPM2 gene expression in acute myelogenous leukemia cells." (PMID 32423430, 2020). "Our research suggests that there is a different regulation of PARP1, PARP2, PARP3, and TRPM2 genes expression in acute myelogenous leukemia cells." (PMID 32423430, 2020). "However, the specific mechanism of PARP-1 in acute myeloid leukemia (AML) remains unknown." (PMID 26314963, 2015). "PARP1, PARP2, and TRPM2 genes at mRNA level deregulate in acute myeloid leukemia cells." (PMID 32423430, 2020). "PARP1 and LIG3 are found up-regulated in acute myeloid leukemia (AML) patients as compared to healthy individuals, and most importantly, their expression was strictly associated with chromosomal translocations occurrence." (PMID 33808562, 2021). "Here, we examined the expression levels of the maincomponents of alt-NHEJ (PARP1 and LIG3) in acute myeloid leukemia (AML) patients and assessed their potential correlationwith the formation of chromosomal translocations." (PMID 29633598, 2018).
Cerebral ischemia (30 papers, 2009 to 2024). Restriction of arterial blood supply to the brain associated with insufficient oxygenation to support the metabolic requirements of the tissue. "Cleavage of PARP-1 by caspase 3 is a hallmark of apoptosis, which has been implicated in several neurological diseases (e.g. cerebral ischemia, AD, multiple sclerosis, PD, traumatic brain injury, and ASD)." (PMID 35351881, 2022). "Excessive activation of PARP1 has been shown to be associated with the pathogenesis of numerous diseases, including energetic failure and vascular collapse in shock, diabetes, cerebral ischemia, endothelial dysfunction in hypertension, atherosclerosis, and heart failure." (PMID 25412407, 2015). "Cleavage of PARP-1 by caspase-3 has been implicated in several neurological diseases e.g. cerebral ischemia, Alzheimer's disease, multiple sclerosis, Parkinson's disease, traumatic brain injury, NMDA-mediated excitotoxicity and brain tumors, especially gliomas." (PMID 21176168, 2010). "Extensive poly-ADP-ribosylation by poly(ADP-ribose) polymerase 1 (PARP1) was suggested as a major mechanism of NAD consumption following oxidative stress induced by brain ischemia or traumatic brain injury." (PMID 37174729, 2023). "Parthanatos, a programmed cell death, is initiated by PARP1 over-reaction to DNA damage, which is seen in neurons in Parkinson's disease, after glutamate excitotoxicity and in brain ischemia." (PMID 33168626, 2021). "In pathophysiological conditions such as ischemic stroke, the over-activation of PARP-1 exerts deleterious effects, as demonstrated in several experimental models of cerebral ischemia." (PMID 33321687, 2020). "PARP-1 activation seems to be the central mediator of cerebral ischemia in men, while caspases/cytochrome C appears to have a more influential role in women." (PMID 33520535, 2020). "Under pathological conditions, such as cerebral ischemia, oxidative stress, hypoglycemia, or excitotoxicity, poly (ADP-ribose) polymerase-1 (PARP-1) is the most efficient depleting enzyme for NAD." (PMID 30778282, 2019). "PARP-1 inhibition has been reported to play a neuroprotective role in neurodegeneration induced by acute brain ischemia." (PMID 30841499, 2019). "Our previous results showed that oxidative/genotoxic stress evoked by Aβ, inflammation processes, and brain ischemia led to activation of PARP1 and accumulation of PAR." (PMID 28698968, 2018). "Increasing evidence has indicated crucial roles of NAD+ and PARP-1 in cell survival under such pathological conditions as cerebral ischemia and SR X-ray exposures." (PMID 24386592, 2013). "Third, based on previous studies regarding the roles of NAD+ and PARP-1 in such diseases as brain ischemia, it is warranted to initiate preclinical trials to determine the effectiveness of NAD+ and PARP inhibitors for treating such diseases as brain ischemia." (PMID 24386592, 2013). "Taken together, these findings suggest that the PARP-1 24-kD fragment can also serve as a powerful therapy for CNS disorders like cerebral ischemia where necrotic cell death predominates within the infarct core." (PMID 21176168, 2010). "Our results are in agreement with previous data showing a rapid PARP-1 activation in neurons after a focal brain ischemia and are also consistent with previous reports showing an activation of PARP-1 in microglial cells." (PMID 19956568, 2009). "Furthermore, TPEN, a membrane-permeable zinc chelator, was found to reduce Zn2+ accumulation in cerebral ischemia animal models by inhibiting PARP-1 activation." (PMID 36046027, 2022). "Other series of studies also showed the beneficial effects of genetically disrupting and pharmacologically inhibiting PARP-1 in cerebral ischemia, oxidative and nitrosative stress in islet cells, myocardial post-ischemic injury, and cerebral artery occlusion and its effect on motor function." (PMID 26218895, 2015).
Cerebral ischemia (continued). "Multiple recent studies have further suggested that PARP-1 may become a promising therapeutic target for cerebral ischemia." (PMID 24386592, 2013). "Thus, the decrease of NAD levels can be resulted from a combination of factors, including the decrease of iNAMPT, the reduction of enzymatic activity of iNAMPT, and an increase of NAD consumption by NAD-dependent enzymes such as PARP-1 after cerebral ischemia." (PMID 24392007, 2013). "The information has also suggested that NAD+ metabolism, PARP-1 and sirtuins may become promising therapeutic targets for cerebral ischemia and radiation damage." (PMID 24386592, 2013). "Silencing/inhibition of MMP-9 and PARP-1 both reduce damage after cerebral ischemia." (PMID 22235301, 2012). "Interestingly, PARP1 activation is known to dysregulate SIRT1 activity via NAD+ depletion during skeletal muscle fatigue, aging, and cerebral ischemia, and deletion of PARP1 results in increased SIRT1 activity, higher mitochondrial content, and increased energy expenditure." (PMID 37744380, 2023). "As reviewed in these articles, cumulating evidence has supported the hypothesis that NAD+ and NAD+-related proteins such as PARP-1 play pivotal roles in cell death and tissue injury under various pathological conditions such as cerebral ischemia and SR X-ray exposures." (PMID 24386592, 2013). "In cerebral ischemia models, MMP-2 cleaves PARP1 and XRCC1, two DNA repair enzymes, in vitro and in vivo to induce neuronal apoptosis." (PMID 39569367, 2024). "For instance, deletion of the Parp1 gene or pharmacological inhibition of PARP enzymatic activity significantly reduces neuronal cell death and infarct size in animal and cell culture models of cerebral ischemia." (PMID 25161822, 2014). "However, the PARP-1-based therapeutic strategy for brain ischemia has significant limitations: first, PARP-1 inhibition appears to be beneficial for relatively severe brain ischemia, while it is not beneficial for relatively mild brain ischemia." (PMID 24386592, 2013).
Hyperglycemia (29 papers, 2010 to 2026). An increased concentration of glucose in the blood. "Under the conditions of hyperglycemia glycolysis, an increase in the production of ROS occurs that causes DNA damage and the activation of poly-ADP-ribose Polymerase 1 (PARP1) which is an enzyme that repairs DNA." (PMID 39674630, 2024). "These species oversee several hyperglycemia-induced pathogenic mechanisms, such as the inhibition of the enzyme glyceraldehyde-3-phosphate dehydrogenase via the activation of the enzyme poly-ADP-ribose polymerase-1 (PARP-1)." (PMID 35669072, 2022). "Hyperglycemia is also associated with PARP-1 hyperactivation that is usually an aggravating factor in the development of systemic diabetic dysfunctions." (PMID 34768872, 2021). "Our previous study demonstrated that hyperglycemia is associated with PARP-1 and NF-κB upregulation and microgliosis in the cerebral cortex, likely in response to oxidative stress." (PMID 29544513, 2018). "In the present study, we investigated the role and underlying mechanism of PARP-1 in hyperglycemia induced DCM." (PMID 27027354, 2016). "Activation of poly-ADP-ribose polymerase 1 (PARP1) in response to hyperglycemia will cause the inhibition of glyceraldehyde-3-phosphate dehydrogenase (GAPDH) activity due to depletion of glycolytic intermediates and resulting in an accumulation of upstream metabolites." (PMID 40843204, 2025). "In addition, a study has suggested that activation of PARP-1 is reported to be associated with hyperglycemia-induced ROS formation, as it is evidenced that PARP inhibitors blocked ROS production." (PMID 24987732, 2014). "Hyperglycemia-induced oxidative stress overactivates PARP1, leading to detrimental effects on cardiac cells." (PMID 40628905, 2025). "Poly (ADP-ribose) polymerase 1 (PARP1) represses TFPI2 in VSMCs under hyperglycemia by promoting DNA methylation." (PMID 40361374, 2025). "Further experiments revealed that hyperglycemia-induced PARP1 promotes diabetic neointimal hyperplasia via down-regulating TFPI-2 (which normally suppresses proliferation of vascular smooth muscle cells)." (PMID 39153052, 2024). "In our previous study, we discovered that TFPI2 was downregulated in hyperglycaemia-stimulated VSMCs, in which PARP1 activation plays a key role in promoting DNA methylation of the TFPI2 promoter and TFPI2 downregulation." (PMID 37915070, 2023). "A hyperactivation of PARP-1, which often occurs at the inflammation, hypoxia, hypo- and hyperglycemia, modulates or activates multiple cellular pathways leading to cell death or degeneration." (PMID 34768872, 2021). "PARP-1 depletion reversed the hyperglycemia-induced synthetic phenotype switching of VSMCs and macrophage polarization by targeting Stat1." (PMID 31924749, 2020). "Mechanistically, our results suggest that PARP-1 regulates hyperglycemia-accelerated arteriosclerotic calcification by targeting Stat1/Runx2 axis." (PMID 31924749, 2020). "We have demonstrated that recurrent hyperglycemia leads to oxidative stress (PARP-1, NF-κB upregulation) and microgliosis in the cerebral cortex, the brain region important for executive function." (PMID 29544513, 2018). "Beneficial effects of Olaparib on lifespan were also ablated by feeding RNAi knock-down of the TCF7L2 homolog, pop-1, suggesting that TCF7L2 is required to gain therapeutic benefit from PARP-1 inhibition in the context of hyperglycemia." (PMID 29392078, 2018). "We analyzed the impact of PARP-1 inhibition on C. elegans health in the setting of hyperglycemia and on glucose-stimulated GLP-1 secretion in human intestinal cells." (PMID 29392078, 2018).